SS18L1 (SS18L1 subunit of BAF chromatin remodeling complex)
Description:
Transcriptional activator which is required for calcium-dependent dendritic growth and branching in cortical neurons. Recruits CREB-binding protein (CREBBP) to nuclear bodies. Component of the CREST-BRG1 complex, a multiprotein complex that regulates promoter activation by orchestrating a calcium-dependent release of a repressor complex and a recruitment of an activator complex. In resting neurons, transcription of the c-FOS promoter is inhibited by BRG1-dependent recruitment of a phospho-RB1-HDAC1 repressor complex. Upon calcium influx, RB1 is dephosphorylated by calcineurin, which leads to release of the repressor complex. At the same time, there is increased recruitment of CREBBP to the promoter by a CREST-dependent mechanism, which leads to transcriptional activation. The CREST-BRG1 complex also binds to the NR2B promoter, and activity-dependent induction of NR2B expression involves a release of HDAC1 and recruitment of CREBBP (By similarity).
Synonyms: CREST; KIAA0693; SMARCL2; LP2261
Tractability: PROTAC: its protein half-life has been measured.
Gene: Protein-coding gene on chromosome 20 (62,143,769 to 62,182,514, forward strand). Ensembl gene ENSG00000184402.
Subcellular location: Nucleus; Chromosome, centromere, kinetochore
Subcellular location (Human Protein Atlas): Cytosol; Nucleoplasm
Pathways (Reactome):
Chromatin organization: Formation of neuronal progenitor and neuronal BAF (npBAF and nBAF); Formation of the canonical BAF (cBAF) complex; Formation of the non-canonical BAF (ncBAF) complex
Developmental Biology: Regulation of MITF-M-dependent genes involved in pigmentation
Gene expression (Transcription): Regulation of endogenous retroelements by Piwi-interacting RNAs (piRNAs)
Gene Ontology:
Molecular function: protein binding; transcription coactivator activity
Biological process: positive regulation of dendrite morphogenesis; positive regulation of DNA-templated transcription; positive regulation of transcription by RNA polymerase II
Cellular component: cytosol; kinetochore; nucleoplasm; nucleus; condensed chromosome, centromeric region; nBAF complex
Genetic constraint (gnomAD): Loss-of-function variants: 32 observed, 71.09 expected, observed/expected ratio (o/e) 0.45, 90% interval 0.34 to 0.61. The upper end of that interval is the gene's LOEUF score, 0.61, which puts it in group 2 of 6, group 1 being the genes least tolerant of losing a copy. Missense variants: 430 observed, 538.58 expected, observed/expected ratio (o/e) 0.8, 90% interval 0.74 to 0.87. Synonymous variants: 237 observed, 232.08 expected, observed/expected ratio (o/e) 1.02, 90% interval 0.92 to 1.14.
Gene-disease validity (ClinGen):
ClinGen rates the evidence that SS18L1 causes each of these diseases.
amyotrophic lateral sclerosis (autosomal dominant): Limited. Amyotrophic lateral sclerosis (ALS) is a neurodegenerative disease characterized by progressive muscular paralysis reflecting degeneration of motor neurons in the primary motor cortex, corticospinal tracts, brainstem and spinal cord.
Homologues: Orthologues: chimpanzee SS18L1 (99% identical), macaque SS18L1 (97% identical), dog SS18L1 (92% identical), mouse Ss18l1 (91% identical), rat Ss18l1 (91% identical), pig SS18L1 (89% identical), guinea pig SS18L1 (86% identical), tropical clawed frog ss18l1 (80% identical), Caenorhabditis elegans ZK973.9 (21% identical). Paralogues in human: SS18 (63% identical), SS18L2 (11% identical).
Diseases named in the same sentence as SS18L1 in open-access papers:
SS18L1 is named in the same sentence as 26 diseases in open-access papers, as found by Europe PMC text mining. Sharing a sentence is not in itself a finding about the gene and the disease. The quoted sentences say what the papers report.
amyotrophic lateral sclerosis (7 papers, 2015 to 2022). "The mutation of the SS18L1 gene is associated with amyotrophic lateral sclerosis (ALS)." (PMID 36046506, 2022). "Interestingly, mutations in the human SWI/SNF gene SS18L1 have been implicated in amyotrophic lateral sclerosis, a neurodegenerative disorder characterized by loss of motor neurons." (PMID 30923190, 2019). "The BAF complex is crucial for mammalian nervous system as mutations in BAF subunits have been implicated in neurological disorders such as Coffin-Siris syndrome due to mutations in BRG1 and BRM, and SS18L1/CREST in amyotrophic lateral sclerosis (ALS)." (PMID 30116172, 2018). "Some paraspeckle proteins, such as TDP-13, FUS, EWS, TAF15, HNRNPA1, SS18L1, and SFPQ have been associated with neuro-degenerative diseases, such as amyotrophic lateral sclerosis (ALS) and frontotemporal dementia (FTD)." (PMID 30087896, 2018). "In this context, it would be intriguing to note that a number of paraspeckle-enriched RBPs with IDRs, including SFPQ, FUS, EWSR1, TAF15, TDP-43, SS18L1 and HNRNPA1, are mutated in familial cases of amyotrophic lateral sclerosis (ALS) and other neurodegenerative diseases." (PMID 30355755, 2018).
synovial sarcoma (5 papers, 2008 to 2025). "SS18 and SS18L1 encode transcriptional regulators and are breakpoints in chromosomal translocations in synovial sarcoma." (PMID 27807467, 2016). "The most notable is a polymorphic Alu insertion in the first intron of the SS18L1 (synovial sarcoma translocation gene on chromosome 18-like 1) gene locus associated with CpG hypermethylation at the same locus (p = 3.67x10-6)." (PMID 27807467, 2016). "For example, a polymorphic Alu insertion in the SS18L1 (Synovial sarcoma translocation gene on chromosome 18-like 1) gene locus oriented anti-sense to the transcription of the gene, is associated with increased methylation of nearby CpG sites at the same gene locus (p = 6.67x10-6)." (PMID 27807467, 2016). "Moreover, SS18L1 is a homolog for the SS18 gene and both SS18 and SS18L1 are detected in patients with synovial sarcoma." (PMID 40176070, 2025). "Nearly 100 percent of synovial sarcomas (SSs) have translocations involving the SS18 component of the BAF (mammalian SWI/SNF) chromatin remodeler complexes or, in rare cases, the homologue protein SS18L1 (CREST)." (PMID 38611033, 2024).
acute B-lymphoblastic leukemia (2 papers, 2024 to 2025). "It is quite interesting to note that a novel MEF2C::SS18L1 gene fusion has been recently discovered in a child with acute B-lymphoblastic leukemia (B-ALL)." (PMID 40176070, 2025).
breast carcinoma (2 papers, 2008 to 2025). "SMARCD2, BCL7C and SS18L1 are amplified in 6%–8% of breast cancer patients from the TCGA and METABRIC breast cancer patient cohorts." (PMID 41278204, 2025).
brain tumors (1 paper, 2011). "STAT3 is a known oncogene recently identified as a driver of mesenchymal transformation in brain tumors, while SS18L1 is a protein normally required for calcium-dependent dendritic growth and branching in cortical neurons." (PMID 21980275, 2011). "Similarly, for the brain tumor case study, NGF identified a key logic function which associates the mesenchymal phenotype with the upregulation of STAT3 and downregulation of SS18L1." (PMID 21980275, 2011).
gastric cancer (1 paper, 2024). A primary or metastatic malignant neoplasm involving the stomach. "This association suggests that SS18L1 may influence the spread of gastric cancer, making it a potential marker or target for therapeutic strategies." (PMID 39185313, 2024).
mucinous tumors (1 paper, 2012). "These include: FH, GMPS, PIK3CA, EIF4A2, ZNF384, and SS18L1 (amplifications in serous tumors); TET2, FGFR10P, NF1, ERBB2, and SH3GL1 (deletions in serous tumors) and ERBB2 (amplifications in mucinous tumors)." (PMID 23078675, 2012).
sarcoma (1 paper, 2014). A usually aggressive malignant neoplasm of the soft tissue or bone. "A pathway analysis indicated enrichment for chromatin regulator genes, such as the synovial sarcoma translocation (SS18L1 or CREST) gene, which contained a single de novo event in one sample." (PMID 24705293, 2014).
cancer (3 papers, 2012 to 2024). A tumor composed of atypical neoplastic, often pleomorphic cells that invade other tissues. "We demonstrate here that the paralogous cancer-related minor SWI/SNF subunits DPF1, -2, -3; BCL7A, -B, -C; and SS18 and SS18L1 reside in BAF-class human SWI/SNF complexes and, that PHF10 marks PBAF SWI/SNF complexes." (PMID 22442726, 2012). "Although there is not any reports of MEF2C::SS18L1 in hematologic tumors at present, the presence of recurrent MEF2C::SS18 fusions in MSA suggests the importance and specificity of this fusion in pathogenesis of malignant tumor." (PMID 38907739, 2024).
nervous system diseases (2 papers, 2018 to 2022). "The functional role of SS18L1 in peripheral nervous system diseases is largely unknown." (PMID 36046506, 2022).
tumor (1 paper, 2024). "SS18L1 has been identified as having copy number variations significantly linked to tumor metastasis." (PMID 39185313, 2024).
SS18L1 also shares sentences with these, for which no sentence is quoted: Telangiectasia (5 papers); CREST syndrome (2); retina degeneration (2); calcinosis (1); Coffin-Siris syndrome (1); esophageal (1); frontotemporal dementia (1); gynecological cancers (1); hematologic tumors (1); Infertility (1); leukemia (1); neuritis (1); neuroblastoma (1); proteinopathy (1); psychiatric diseases (1).